NUSAP1 (nucleolar and spindle associated protein 1)
Description:
Microtubule-associated protein with the capacity to bundle and stabilize microtubules (By similarity). May associate with chromosomes and promote the organization of mitotic spindle microtubules around them.
Synonyms: NuSAP; ANKT; FLJ13421; LNP; SAPL; BM037; PRO0310p1; Q0310
Tractability: PROTAC: UniProt records ubiquitination sites on it; ubiquitination databases record sites on it; its protein half-life has been measured.
Gene: Protein-coding gene on chromosome 15 (41,320,794 to 41,381,054, forward strand). Ensembl gene ENSG00000137804.
Subcellular location: Cytoplasm; Nucleus, nucleolus; Cytoplasm, cytoskeleton, spindle; Chromosome
Subcellular location (Human Protein Atlas): Nucleoli; Nucleoli fibrillar center; Nucleoplasm
Gene Ontology:
Molecular function: protein binding; RNA binding; microtubule binding
Biological process: establishment of mitotic spindle localization; mitotic chromosome condensation; mitotic cytokinesis; mitotic sister chromatid segregation; positive regulation of mitotic nuclear division; microtubule cytoskeleton organization
Cellular component: mitotic spindle; nucleolus; chromosome; cytoplasm; microtubule; spindle
Genetic constraint (gnomAD): Loss-of-function variants: 18 observed, 25.52 expected, observed/expected ratio (o/e) 0.71, 90% interval 0.49 to 1.05. The upper end of that interval is the gene's LOEUF score, 1.05, which puts it in group 4 of 6, group 1 being the genes least tolerant of losing a copy. Missense variants: 305 observed, 333.25 expected, observed/expected ratio (o/e) 0.92, 90% interval 0.83 to 1.01. Synonymous variants: 136 observed, 124.82 expected, observed/expected ratio (o/e) 1.09, 90% interval 0.95 to 1.26.
Homologues: Orthologues: chimpanzee NUSAP1 (98% identical), macaque NUSAP1 (90% identical), dog NUSAP1 (76% identical), pig NUSAP1 (72% identical), rabbit NUSAP1 (70% identical), guinea pig NUSAP1 (65% identical), mouse Nusap1 (62% identical), rat Nusap1 (62% identical), tropical clawed frog nusap1 (41% identical), zebrafish nusap1 (33% identical).
Diseases named in the same sentence as NUSAP1 in open-access papers:
NUSAP1 is named in the same sentence as 100 diseases in open-access papers, as found by Europe PMC text mining. Sharing a sentence is not in itself a finding about the gene and the disease. The quoted sentences say what the papers report.
breast cancer (26 papers, 2013 to 2025). A primary or metastatic malignant neoplasm involving the breast. "The high expression of NUSAP1 gene is associated with poor patient overall survival, and this gene also serves as a prognostic factor in breast cancer." (PMID 38741183, 2024). "In breast cancer, NUSAP1 has been associated with poor overall survival and infiltration of various immune cells." (PMID 38441732, 2024). "Like MELK, NUSAP1 is a protein kinase that promotes cell proliferation and survival, and its overexpression in breast cancer patients has been linked to a poor prognosis." (PMID 38084295, 2023). "High expression of NUSAP1 has been linked to more aggressive breast cancer phenotypes and worse overall survival." (PMID 38084295, 2023). "Nucleolar and Spindle Associated Protein1 (NUSAP1) inhibits the proliferation of invasive breast cancer cells by regulating DLGAP5 expression." (PMID 34298705, 2021). "In breast cancer tissues, ANKRD22 promoted breast cancer cell malignancy by activating the Wnt/β-catenin pathway by regulating nucleolar and spindle-associated protein 1 (NuSAP1) expression." (PMID 34584137, 2021). "ANKRD22 knockdown suppressed the proliferation, invasion, and EMT of breast cancer cells and the underlying mechanism was through regulating NuSAP1." (PMID 32651974, 2021). "Five hub genes, RRM2, TOP2A, PBK, MELK, and NUSAP1, which are associated with breast cancer pathogenesis, are gradually upregulated from NME to DCIS and then downregulated in IDC." (PMID 34094915, 2021). "The high expression of the NUSAP1 gene has been associated with poor prognosis in melanoma patients, with a malignancy-risk genetic signature in breast cancer and with recurrence in prostate cancer." (PMID 23756599, 2013). "High NUSAP1 expression promotes malignant biological behaviors, such as tumor invasion and metastasis, and is associated with poor prognosis in patients with astrocytoma, breast cancer, colon cancer, and cervical cancer." (PMID 35739489, 2022). "However, the association between the expression of NuSAP1 and breast cancer subtypes bordered on significant (P = 0.063)." (PMID 26485712, 2015). "Besides, many studies also showed that overexpression of NUSAP1 was associated with poor survival of colon cancer, astrocytoma, glioblastoma multiforme, renal cell carcinoma, prostate cancer, breast cancer, and esophageal squamous cell carcinoma." (PMID 34354737, 2021). "Increased expression of NUSAP1 has been reported in prostate cancer, breast cancer, oral squamous cell carcinoma, and cervical cancer and is closely associated with tumor development and a poor prognosis." (PMID 38229038, 2024). "We found that NUSAP1 expression was significantly upregulated in E2-treated breast cancer cells compared to the vehicle-treated control in GSE46924 dataset." (PMID 39430250, 2024). "NUSAP1 participates in regulating the Wnt/β-catenin signaling pathway and is expressed at higher levels in breast cancer and liver cancer tissues than in corresponding normal tissues." (PMID 38229038, 2024). "Consistently, analysis of GSE4668 dataset showed a concentration-dependent increase of NUSAP1 expression in breast cancer cells treated with increasing concentrations of E2, indicating that E2 positively regulates NUSAP1 expression." (PMID 39430250, 2024). "NUSAP1 affect tumor growth by regulating the AMPK signaling pathway has been reported in tumors such as breast cancer and gastric cancer." (PMID 38229038, 2024). "Intriguingly, through analysis of GSE22533 dataset which comprises fulvestrant treatment data, we found that NUSAP1 was markedly downregulated upon fulvestrant treatment in both breast cancer and liver cancer cell lines." (PMID 39430250, 2024). "High levels of NUSAP1 have been associated with proliferation, invasion, and metastasis in non-small cell lung cancer (NSCLC) 9, pancreatic cancer 8, and breast cancer 11, prostate cancer 13, liver cancer." (PMID 37781040, 2023).
breast cancer (continued). "Recently, several studies have investigated the prognostic value of various genes in breast cancer, including NUSAP1, maternal embryonic leucine zipper kinase (MELK), and CDK1." (PMID 38084295, 2023). "Overall survival analysis of NUSAP1, MELK, and CDK1 in breast cancer patients has provided valuable insights into the underlying mechanisms of tumor progression." (PMID 38084295, 2023). "Our results demonstrated that nucleolar and spindle-associated protein 1 (NUSAP1), melatonin receptor 1A (MELT), and cyclin-dependent kinase 1 (CDK1) are three hub genes that play pivotal roles in the pathogenesis of breast cancer." (PMID 38084295, 2023). "Numerous studies have confirmed that NUSAP1 is upregulated in breast cancer, hepatocellular carcinoma, and other malignant tumors, and is closely related to malignant biological behaviors, such as cell cycle regulation, invasion, and metastasis." (PMID 35739489, 2022). "High NUSAP1 expression predicts poor prognosis in astrocytoma, breast cancer, esophageal squamous cell carcinoma, and colon cancer." (PMID 35739489, 2022). "NUSAP1 overexpression has been reported in bladder, cervical, colon, liver, lung, prostate, kidney, and breast cancers, glioblastoma, and oral squamous cell carcinoma; multiple studies have correlated its overexpression with poor prognosis." (PMID 36478748, 2022). "NUSAP1 is highly expressed in multiple malignant tumors, such as breast cancer, hepatocellular carcinoma, esophageal squamous cell carcinoma, and glioblastoma." (PMID 35739489, 2022). "This study shows that hub genes associated with breast cancer pathogenesis, namely RRM2, TOP2A, PBK, MELK, and NUSAP1, are gradually upregulated from NME to DCIS and then downregulated in IDC." (PMID 34094915, 2021). "NuSAP1 was also previously reported to be highly expressed in breast cancer and involved in breast cancer progression." (PMID 32651974, 2021). "Hub genes, namely TOP2A, MELK, PBK, NUSAP1, and RRM2, are closely associated with the occurrence and pathogenesis of breast cancer." (PMID 34094915, 2021). "Previous studies suggested that NUSAP1 was abnormally elevated in numerous tumors including liver cancer, breast cancer, prostate cancer, gastric cancer, and bladder cancer." (PMID 34782617, 2021). "High expression of NUSAP1 correlates with the adverse prognosis of cervical cancer and breast cancer." (PMID 34782617, 2021). "NuSAP1 also served as a key regulator of breast cancer progression, and it contributed to cell proliferation and invasion." (PMID 32651974, 2021). "Recent evidences suggested that silencing NUSAP1 inhibits proliferation, migration, and invasion of glioma, breast cancer, liver cancer, and colorectal cancer." (PMID 34782617, 2021). "Previous studies found that high expression of NuSAP1 was significantly correlated with poor prognosis of breast cancer and melanoma." (PMID 32651974, 2021). "The inhibitory effects of ANKRD22 knockdown on the proliferation, invasion, and EMT of breast cancer cells were reversed by NuSAP1 overexpression." (PMID 32651974, 2021). "We observed that G2M checkpoint, MYC target V2, and breast cancer ZNF217 were differentially enriched in the high NUSAP1 expression phenotype." (PMID 32226503, 2020). "NUSAP1 upregulation is detected in a broad range of human cancers, such as prostate cancer, astrocytoma, lung cancer, and breast cancer." (PMID 33489890, 2020). "Although overexpression of NUSAP1 has been found in breast cancer, hepatocellular carcinoma and pancreatic cancer, there is no study demonstrating the altered expression profile of NUSAP1 in oral cancer." (PMID 26554377, 2015). "The current study investigated the correlation between NuSAP1 expression and the prognosis of different subtypes of breast cancer, particularly TNBC." (PMID 26485712, 2015). "Moreover, NUSAP1 expression levels seem to be concomitant with the tumor infiltration of various immune cells in breast cancer." (PMID 37781040, 2023).
breast cancer (continued). "Moreover, we perform in vitro cellular experiments to validate the regulatory function of NUSAP1 on cell proliferation using breast cancer and lung adenocarcinoma cell lines." (PMID 37781040, 2023). "High expression of NuSAP1 was correlated with poor prognosis of breast cancer and melanoma." (PMID 32651974, 2021). "In summary, this study demonstrated that ANKRD22 enhanced breast cancer cell malignancy by activating the Wnt/β-catenin pathway via modulating NuSAP1 expression, which might shed light on new therapeutic approaches for breast cancer." (PMID 32651974, 2021). "Studies have also confirmed that NUSAP1 has a high prognostic value for breast cancer." (PMID 32420375, 2020). "This study investigated the prognostic value of NuSAP1 in breast cancer." (PMID 26485712, 2015). "A Kaplan-Meier analysis was used to estimate the prognostic value of NuSAP1 in breast cancer." (PMID 26485712, 2015). "In conclusion, our study confirmed the prognostic value of NuSAP1 in breast cancer." (PMID 26485712, 2015). "In all patients with combination of two cohorts, similar trends were found with P < 0.001; further analysis of the prognostic value of NuSAP1 in four subtypes of breast cancer revealed that NuSAP1 expression was significantly correlated with poor DFS in triple-negative subgroup (P < 0.001)." (PMID 26485712, 2015). "Our study confirms the prognostic value of NuSAP1 in breast cancer." (PMID 26485712, 2015). "Therefore, we investigated whether ANKRD22 could regulate NuSAP1 expression by activating the Wnt/β-catenin signaling pathway in breast cancer." (PMID 32651974, 2021). "Therefore, we concluded that high expression of ANKRD22 could facilitate the progress of breast cancer, at least partially, by activating Wnt/β-catenin signaling via NuSAP1." (PMID 32651974, 2021). "In view of the potentially important role of NuSAP1 in the development of breast cancer, along with the predicted relationship between NuSAP1 and ANKRD22 from the Cancer Genome Atlas (TCGA) database, it may be possible that ANKRD22 affects the development of breast cancer via NuSAP1." (PMID 32651974, 2021). "qRT-PCR assay confirmed the positive correlation between the expression levels of NUSAP1 and ANKRD22 in breast cancer tissues from 53 patients." (PMID 32651974, 2021). "The NUSAP1 overexpression vector and ANKRD22 shRNA plasmids were co-transfected into breast cancer cells." (PMID 32651974, 2021). "Our results demonstrate that CESC patients with high NUSAP1 expression were enriched in the G2M checkpoint, MYC targets, and breast cancer ZNF217, which are closely related to the early onset of cancer and the risk of tumor progression and metastasis." (PMID 32226503, 2020). "report that NUSAP1 depletion suppresses cell proliferation, migration, and invasion by regulating CDK1 and DLGAP5 expression in invasive breast cancer cells." (PMID 33489890, 2020). "GSEA demonstrated that CESC patients with high expression of NUSAP1 were enriched in the G2M checkpoint, MYC targets, and breast cancer ZNF217." (PMID 32226503, 2020). "However, the NuSAP1 expression status of the subtypes of breast cancer remains unknown." (PMID 26485712, 2015). "Furthermore, our research has shown that MELK, NUSAP1, and CDK1 are crucial hub genes that are overexpressed in breast cancer and have potential roles as biomarkers." (PMID 38084295, 2023). "In addition, NUSAP1, similar to BRCA1, plays a role in DNA double-stand break repair via the homologous recombination and single-strand annealing pathways in breast cancer, and it protects BRCA1 from proteasome-mediated degradation." (PMID 35739489, 2022). "Moreover, overexpression of NUSAP1 reversed the inhibitory effects of ANKRD22 knockdown on the proliferation, invasion, and EMT of breast cancer cells." (PMID 32651974, 2021).
breast cancer (continued). "In addition, sequencing results illustrate significant decreased expression of the Nusap1 gene, which has been shown to regulate levels of BRCA1, an extensively studied tumour suppressor gene involved in double strand breaks and breast cancer." (PMID 27014724, 2016). "To further investigate the correlation between NuSAP1 expression and breast cancer prognosis, particularly for different subtypes, we constructed two sets of TMAs that contained 450 stage I to III primary breast cancer tissues and determined the NuSAP1 expressions via immunostaining." (PMID 26485712, 2015).
glioma (23 papers, 2017 to 2025). A benign or malignant brain and spinal cord tumor that arises from glial cells (astrocytes, oligodendrocytes, ependymal cells). "In gliomas, elevated NUSAP1 expression has been associated with increased tumor aggressiveness, poor prognosis, and treatment resistance." (PMID 39975552, 2025). "NUSAP1-based risk models hold potential as predictive and therapeutic tools for personalized glioma treatment." (PMID 39975552, 2025). "In conclusion, a thorough prognostic categorization and immune evaluation of glioma patients can be effectively executed through NUSAP1-linked methodologies." (PMID 39975552, 2025). "This indicates that NUSAP1 may be utilized as a diagnostic marker of glioma and GBM at an early stage." (PMID 32317623, 2020). "In recent years, researchers have discovered a link between NUSAP1 and cancer, high levels of NUSAP1 have been linked to the development, advancement, and unfavorable prognosis of various tumors, including esophageal squamous cell carcinoma, prostate cancer, renal cell carcinoma and glioma." (PMID 38441732, 2024). "Given the genetic and microenvironmental similarities between glioma and glioma, these insights support the potential of targeting NUSAP1 in glioma treatment." (PMID 39975552, 2025). "Through NUSAP1 knockdown experiments, we elucidated its pivotal role in regulating glioma cell proliferation, migration, and distant metastasis." (PMID 39975552, 2025). "In state 2, C1 AKAP9-expressing glioma cells dominated, while in state 3, C2 NUSAP1-expressing glioma cells were the most abundant." (PMID 39975552, 2025). "In our investigation of NUSAP1’s influence on glioma, we conducted NUSAP1 gene knockdown via transfection, with confirmation of transfection efficiency using RT-qPCR." (PMID 39975552, 2025). "The results indicated that inhibition of NUSAP1 led to reduced colony sizes in both U251 and LN229 cells, suggesting that downregulation of NUSAP1 impedes glioma cell proliferation." (PMID 39975552, 2025). "In conclusion, our findings provide new insights into the potential application of NUSAP1 in personalized glioma treatment." (PMID 39975552, 2025). "Our findings extend this knowledge to glioma, revealing similar mechanisms by which NUSAP1 contributes to tumorigenesis." (PMID 39975552, 2025). "While NUSAP1 is recognized as an oncogene in several cancers, its role in glioma remains inadequately understood." (PMID 39975552, 2025). "Studies have confirmed that multiple miRNAs can target NUSAP1 acting as an upstream regulators in various malignant tumors except glioma, such as miR-193a-5p, miR-758-3p, miR-569, and miR-769-5p." (PMID 36982952, 2023). "qPCR analysis of mice glioma specimens confirmed that NUSAP1 expression was indeed downregulated with the decrease of LINC01393." (PMID 36982952, 2023). "Next, through both in vivo and in vitro experiments, we demonstrated that LINC01393 served as a sponge for miR-128-3p and rescued expression of NUSAP1 to promote glioma progression." (PMID 36982952, 2023). "It is worth pointing out that in glioma (Glioma_GSE131928), NUSAP1 was predominantly expressed in malignant cells, monocyte, and macrophage, but not in T-proli." (PMID 37781040, 2023). "NUSAP1 silencing results in proliferation arrest, cell death in glioma cells, and formation of supernumerary centrosomes." (PMID 34885051, 2021). "In gliomas, NUSAP1 is overexpressed, and expression is correlated with tumor grade and overall survival." (PMID 34885051, 2021). "NUSAP1 is a prognostic factor for gliomas, and silencing NUSAP1 can inhibit GBM cell proliferation both in vivo and in vitro." (PMID 33423377, 2021). "Subsequent validation and utilization of this clinical significance requires large-scale analysis of NUSAP1 levels in patients at each grade of glioma." (PMID 32317623, 2020).